FAP (fibroblast activation protein alpha)
Diseases named in the same sentence as FAP in open-access papers (continued):
Sharing a sentence is not in itself a finding about the gene and the disease.
tumor (continued). "As the stroma volume can be larger than the tumor volume, stroma-targeted PET imaging may be more sensitive than glycolysis PET imaging for detecting small lesions with sufficient FAP-expressing stroma." (PMID 34671627, 2021). "The results showed that CAFs were located in the tumor stroma by staining α-SMA and FAP." (PMID 34930321, 2021). "Primary CCRCCs with metachronous metastases showed also higher rate of FAP positivity than non-metastatic ones, and this difference was significant at the tumour centre." (PMID 33207686, 2020). "FAP expression in both tumour areas did not vary significantly in any case (Chi-square test, p > 0.05 in all cases) (data not shown in figures or tables)." (PMID 33207686, 2020). "FAP positive CAF secrete high levels of CCL2 which in turn addresses the CCL2 receptor (CCR2) on circulating MDSC, activating immunosuppressive STAT3 signaling and leading to an enrichment of MDSC in tumor tissues." (PMID 32899119, 2020). "Additionally, another study has shown that FAP+ CAFs secrete CXCL12, which coat the tumor cells and block the accumulation of CD8+ T cells to the proximity of the tumor." (PMID 32752017, 2020). "Three primary tumors lacked FAP expression; one gained expression at recurrence while the other two still lacked expression in the recurrent tumor." (PMID 33082953, 2020). "Depleting FAP+ fibroblasts in immunodeficient mice did not impact tumor growth, suggesting that the tumor-promoting role of the FAP+ CAFs is not due to direct impacts on tumor cells, but rather through manipulations of the immune response." (PMID 33198201, 2020). "This analysis revealed that 14/16 primary tumors (87.5%) and 11/13 recurrent tumors (84.6%) displayed some level of FAP staining within the main tumor parenchyma, while 0/9 adjacent nontumor areas (0%) stained positive." (PMID 33082953, 2020). "CAFs in tumours were evaluated by immunohistochemistry for α‐SMA and FAP." (PMID 32783302, 2020). "Interestingly, most cells expressing α‐SMA, FAP‐α or PDGFR‐α are GFP‐positive in both groups (Fig EV2C), demonstrating that most CAFs present in the tumour, at the time of sacrifice, originate from the grafted fibroblasts." (PMID 33025708, 2020). "The expression of FAP in carcinomas is generally limited to the stromal CAF population, with FAP being largely absent from the tumor cells themselves." (PMID 33082953, 2020). "Because these functions can be critical to tumor progression and since FAP is virtually absent from healthy cells, 12 FAP has emerged as a promising target for selective delivery of imaging and therapeutic agents to solid tumors." (PMID 32483418, 2020). "Recent studies on fibroblast heterogeneity have demonstrated that FAP is not homogenously expressed on tumor fibroblasts but, rather, expressed on yet-to-be fully defined subsets of fibroblasts." (PMID 33153037, 2020). "This regression was likely related to OV targeting of FAP-expressing CAFs present in the model, as the tumor cells were shown to be FAP negative." (PMID 33167307, 2020). "In addition, targeting FAP by DNA vaccines efficiently promoted CD8+ T cell-mediated repression of CAFs, thereafter elevating intra-tumor chemotherapeutic drug uptake in multi-drug-resistant tumors." (PMID 33292459, 2020). "These expression patterns suggest FAP as a valuable immunotherapy target antigen unlikely to elicit on‐target/off‐tumor toxicity." (PMID 33082953, 2020). "While the most widely described function of FAP on CAFs in CRC was extracellular matrix remodeling, new evidence suggests that FAP on CAFs also has critical roles in regulating antitumor immune response by inducing tumor-promoting inflammation." (PMID 32733792, 2020). "However, we did not attempt to control thiourea bond formation during Df-Bz-NCS conjugation, since the radiopharmaceutical’s affinity for FAP and the large Bmax observed with the U87MG cell line was considered sufficient for effective tumor targeting." (PMID 32806623, 2020).
tumor (continued). "Moreover, little is known about the molecular role of FAP in CRC and its potential in modulating the tumor microenvironment." (PMID 32733792, 2020). "Furthermore, whole body NIRF imaging revealed retention of tumor fluorescence for 32–48 h post-injection in both low and high HER2 expressing as well as in FAP-expressing xenograft models." (PMID 33076292, 2020). "A Phase 2 trial of FAP inhibition using the humanized monoclonal antibody sibrotuzumab failed to slow tumor progression in colorectal cancer patients (NCT02198274)." (PMID 33333727, 2020). "Tumours that invaded locorregional lymph nodes showed higher FAP expression, both at the tumour centre and border, than in tumours that did not invade." (PMID 33207686, 2020). "Thus, FAP may be a particularly relevant immunotherapy target antigen, despite its heterogeneity of expression, because it would allow targeting of the invasive and/or stem‐like cells responsible for continued tumor growth and disease recurrence after standard treatments." (PMID 33082953, 2020). "Bi-FAP/HER2 showed deep penetration into a poorly vascularized, high HER2-expressing tumor." (PMID 33076292, 2020). "In the tumor microenvironment, an increase in transforming growth factor (TGF) levels can induce NAFs to undergo a phenotypic change to CAFs and to express specific proteins, such as α-smooth muscle actin (α-SMA) and fibroblast activation protein (FAP)." (PMID 30992392, 2019). "In order to simultaneously target cancer cells through virus-mediated oncolysis and to re-direct immune responses towards tumor stroma fibroblasts, we engineered the genome of the oncolytic adenovirus ICO15K to express a FAP-targeting BiTE (FBiTE) (named as ICO15K-FBiTE)." (PMID 30683154, 2019). "We conclude that targeting FAP and CAFs in combination with radiation is capable of enhancing anti-tumor T cell infiltrate and function, but does not result in sufficient tumor clearance to extend survival." (PMID 30726287, 2019). "We have previously demonstrated that 82.72% (67/81) stromal fibroblasts in the invasive front of DCIS with microinvasion at the tumor-host interface showed significant FAP-a positivity, and all of the 67 cases of IDC exhibited strongly positive FAP-a staining in stromal fibroblasts." (PMID 31921678, 2019). "Similarly, co-introduction of anti-FAP and anti-tumor CAR T cells has also shown to enhance anti-tumor immunity in xenografted immunodeficient mouse models." (PMID 31462327, 2019). "Actually, CAFs have heterogeneous origins (resident-tissue derived fibroblasts, bone-marrow cells derived fibroblasts, vasculature system cells derived fibroblasts and cancer cells EMT), phenotypes (FAP, α-SMA, PDGFR-A, FSP-1), and functions (tumor-promoting or tumor-suppressive)." (PMID 30646925, 2019). "The high expression of various collagens and metalloproteases confirms the mesenchymal origin of these samples, whereas expression of FAP, a serine protease, indicates the reactive nature of nontransformed tumor stroma." (PMID 31817155, 2019). "We evaluated the effect of FAP inhibition on CAF numbers and found that blockade of FAP function did not alter the number of CAFs in the tumor by IHC or FACS." (PMID 30726287, 2019). "Besides, markers of fibroblast activation, such as α-SMA, FAP, and FSP1, were also obviously decreased in sh-INHBA-transduced tumor xenografts." (PMID 31827640, 2019). "Of note, CAR T cells targeting FAP resulted in variable tumor growth delay in different tumor models, but survival data was not reported." (PMID 30726287, 2019). "In a murine liver tumor model, it was also shown that FAP+ CAFs are a major source of CCL2 and that fibroblastic STAT3-CCL2 signaling promotes tumor growth by enhancing the recruitment of MDSCs, which also predicts poor prognosis of patients with intrahepatic cholangiocarcinoma." (PMID 29545811, 2018).
tumor (continued). "As IL-6 was a regulator of the FAP+ HO-1+ TAM phenotype in this model, we analysed pulmonary metastasis in 4T1 tumours grown in Il6−/− mice, and in agreement, found significantly fewer metastases in the absence of host-derived IL-6, demonstrating that IL-6 played a key role in the process." (PMID 30054470, 2018). "However, as FAP+ stromal cells also play important roles in the periphery, off-tumor targeting of these populations by CAR T-cells results in cachexia and hematological toxicities in murine models, raising potential concern over FAP as a target." (PMID 29872437, 2018). "CEA-IL-2v and FAP-IL-2v demonstrated superior safety, pharmacokinetics and tumor targeting, while lacking preferential induction of Treg cells due to abolished CD25 binding." (PMID 30619269, 2018). "FAP inhibition enhances NK92 killing of PSCs in vitro and enhances PDAC tumor clearance in vivo." (PMID 30400822, 2018). "Tumor accumulation of 68Ga-FAPI-02 was assessed by small-animal PET imaging of mice bearing xenografts from both human FAP-expressing and human FAP-negative tumor cells." (PMID 29626120, 2018). "In this setting, FAP+ TAMs, which highly expressed Hmox1, were exclusively populating the 4T1 and not the E0771 tumours." (PMID 30054470, 2018). "So circulating FAPα source may come from multiple normal tissues, and lower levels of plasma FAPα in ESCC may be a systemic reaction to the presence of tumor." (PMID 28415791, 2017). "In the tumour microenvironment, depletion of FAP+ cells enhances intratumour T cell infiltration, relieves metabolic stress on and delays the exhaustion of CD8+ T cells and enhances TNF and IFN-γ dependent hypoxic killing of tumour cells by T cells." (PMID 28158223, 2017). "A lack of an adequate amount of myofibroblasts collected of the tumour stromal compartment compared to the normal stromal compartment seems not to be the main cause since ACTA2 and FAP are also expressed in myofibroblasts and show an opposing result." (PMID 28531107, 2017). "FAP has enzymatic and non-enzymatic functions in the growth, immunosuppression, invasion and cell signalling of tumour cells." (PMID 28158223, 2017). "Their data showed an increased survival; however, their anti-human FAP scFv did not have cross-reactivity with mouse FAP, which limited their ability to evaluate the on-target/off-tumor toxicity." (PMID 28331617, 2017). "Both tumour-promoting and tumour suppressing roles of FAP by enzymatic and non-enzymatic means have been described." (PMID 28158223, 2017). "MM-BMSCs act as a protectant for bortezomib-induced apoptosis in MM cells through FAPα/β-catenin pathway; however, the other tumor promoting effect, such as immunosuppression, has not yet been fully elucidated." (PMID 28881756, 2017). "The upregulated proteolytic enzyme FAP and SPARC are also signs of a tumor-specific matrix." (PMID 29176937, 2017). "FAP, a serine protease expressed in the reactive stromal fibroblasts of epithelial cancers and the granulation tissue of healing wounds, was also found significantly overexpressed in the CAS of our canine tumour specimens by RT-qPCR." (PMID 28531107, 2017). "Specific targeting and retention to tumor and fibroblast spheroid areas was demonstrated using tumor- and fibroblast-targeted IgG-IL2v (CEA-IL2v and FAP-IL2v, respectively), along with enhanced leukocyte infiltration, activation, and subsequent elimination of tumor cells." (PMID 27858101, 2017). "We further examined the expression of FAPα of fibroblasts treated with the supernatant of Eca-109 tumor cells, but no FAPα expression was detected in fibroblasts." (PMID 28415791, 2017). "An immunohistochemical study using a pilot batch of cases showed that FAP protein was mainly expressed in the stromal cells but not in the tumor cells." (PMID 27936466, 2017). "Furthermore, in our research, we have developed a new tumor vaccine, FAP α τ-MT, which was produced by conjugating 1-MT to a FAP α." (PMID 26985769, 2016).
tumor (continued). "FAP heterodimers which composed by FAP α and FAP β participate in the migration of fibroblasts to collagen substrates, probably because together they can effectively degrade the substrate and regulate tumor cell growth, differentiation, adhesion, metastasis." (PMID 26985769, 2016). "Furthermore, when FAP α expression was inhibited, tumor shrinkage was seen accompanied by increased expression of IFN-γ and TNF-α, indicating the existence of immune suppression that was restricted to the FAP α+ cells." (PMID 26985769, 2016). "FAP is not expressed by mature tissues except for activated fibroblasts during wound healing and in tumor stroma." (PMID 26954362, 2016). "Clinical studies have demonstrated safety of anti-FAP infusion into patients with colorectal carcinoma, metastatic colorectal cancer, and small cell lung cancer although no tumor response has been observed." (PMID 26798356, 2016). "Although FAP reportedly cleaves type I collagen and contributes to tumor progression, the specific pathophysiologic role of FAP is not clear." (PMID 26934296, 2016). "FAP reduction decreased transcripts for IL-10, TGF-β, CCL5 and CCL22 from CD14+ cells, of which 20-40% were F4/80+ TAMs; CCL5 transcripts were also reduced in tumor cells." (PMID 26943036, 2016). "The patient-pooled analysis revealed that the FAP expression level did not significantly correlate with tumor histological differentiation (OR: 0.55, 95% CI: 0.22–1.37, P = 0.197)." (PMID 25775399, 2015). "One possible explanation for this result is that CT26 cells are inherently immunogenic when inactivated by irradiation and that the level of anti-tumor immunity achieved using irradiated non-transduced cells was similar to those using FAP-transduced cells." (PMID 26394925, 2015). "Approximately 90% of reactive stromal fibroblasts of epithelial tumors, but not malignant tumor cells, overexpress FAPα." (PMID 25593080, 2015). "FAP has type I collagen-specific collagenase activity in vitro, supporting the idea that FAP might be an ECM-degrading protease in the invasion and migration of tumor cells." (PMID 24551161, 2014). "A function of FAP independent of its proteolytic activity has also been observed in tumor cells after forced expression." (PMID 24551161, 2014). "Tumor cells were lysed in 1% Triton X-100, and subjected to immunoblot analysis using antibodies specific to TSP-1, a-smooth muscle actin, and fibroblast activated proteins (FAP)." (PMID 26273699, 2014). "Using a specific anti-FAP monoclonal antibody, FAP was detected in the cytoplasm of tumor cells, but was absent from osteocytes in the background bone tissues." (PMID 24520291, 2014). "Talabostat slightly decreased the growth rates of the FAP-α -expressing tumours but the growth retardation was likely not related to the inhibition of FAP-α or the related post-prolyl peptidase dipeptidyl peptidase IV." (PMID 24885257, 2014). "This is consistent with our observation that co-targeting tumor antigen and FAP induces systemic T cells responses against tumor antigen not present in the vaccine." (PMID 24349329, 2013). "FAP-based CAF-targeting therapeutic approaches using their neutralising antibodies, inhibitors, prodrugs and DNA vaccine showed attenuation in tumour growth via improving tumoural immune response in different experimental mouse tumour models." (PMID 24216702, 2013). "The combination of such an anti-FAP vaccine with doxorubicin brought about an inhibition of tumor growth and complete tumor rejection in half of the tested mice whereas there was no survival with doxorubicin treatment alone." (PMID 22949815, 2012). "Although initial studies using antibodies against activated fibroblast proteins, like FAP, did not obtain objective tumor responses." (PMID 22712570, 2012).
tumor (continued). "Here we describe for the first time a much higher expression of ADAM23, FAP, GNPNB and PRSS3 in EC derived from six tumor samples than in EC from four normal tissue specimens examined by real-time PCR, whose origin differed from that investigated by microarray analysis." (PMID 18447899, 2008). "FAP is a 93 kDa cell surface antigen of reactive tumour stromal fibroblasts that is not detected by immunocytochemistry in normal fibroblasts." (PMID 17311675, 2007). "CAFs also express fibroblast activation protein (FAP), a 93 kDa cell surface protein of reactive-tumour stromal cells that is not present in most normal human adult tissue." (PMID 17311675, 2007). "Immunohistochemical staining of colorectal carcinomas and breast cancer confirmed the specific expression of FAP by tumour stroma fibroblasts but not by malignant cells themselves." (PMID 17105646, 2006). "FAP radiotracers demonstrate rapid accumulation in lesions, while the background signal on PET remains vastly low, a biodistribution feature that could be promising for the imaging of a variety of tumor entities." (PMID 41101974, 2026). "FAP‐targeting radiopharmaceuticals labeled with long‐lived radionuclides have shown minimal or no clinical efficacy, as their physical decay half‐lives do not match the tumor retention of the targeting vector." (PMID 40888104, 2026). "Beyond FAP, signaling pathways such as Galectin-1 (Gal-1), the fibroblast growth factor receptor (FGFR)-Gremlin-1 axis, and glucocorticoid (GR) receptor signaling have emerged as key mediators of tumor–stroma crosstalk, particularly in treatment-resistant disease." (PMID 41198614, 2025). "While FAP remains a valuable marker for exploring stromal dynamics within the tumor microenvironment, relying on it alone may not adequately distinguish the CAF population." (PMID 39751643, 2025). "FAP, being overexpressed on CAF cells and present in soluble form (sFAP) in the extracellular matrix, is one of the crucial elements of TME that contributes to the remodeling of the ECM and degradation of the links within the tumor tissue, thereby simplifying its potential metastatic activity." (PMID 40704837, 2025). "Subsequently, we assessed the infiltration levels of each fibroblast subtype across different tissues, noting that FAP+ fibroblasts predominantly resided within tumor regions while MCAM+ fibroblasts were notably observed in normal region indicating their biological heterogeneity." (PMID 40438108, 2025). "Therefore, the mechanism of FAP-directed therapies like huB12-MMAE likely involves modulating the immune microenvironment, inducing a pro-inflammatory response, and promoting its targeted attack on the tumor." (PMID 41154598, 2025). "Although the main source of FAP is fibroblasts, its expression is not confined solely to these cells and can also be detected in other cell types, including mesenchymal-like tumor cells, which may not consistently express cytokeratin (CK)." (PMID 39751643, 2025). "These CAF–tumor interactions are now targeted therapeutically: agents against fibroblast activation protein (FAP) on CAFs (e.g., FAP-specific CAR-T cells or inhibitors) and inhibitors of CAF-derived signals (e.g., TGF-β or IL-6 blockade) are being explored to disrupt the tumor-supportive stroma." (PMID 41409250, 2025). "Notably, EGR1‐high tumours (MP7‐dominant) exhibited strong enrichment of the CAF marker FAP and a striking absence of CD8 T cell infiltration." (PMID 40292733, 2025). "Accordingly, we found a significant negative correlation (p = 0.022, ρ = −0.38) between the expression levels of FAP and PAX5 in the DLBCL and FL tumor tissues, and FAP expression further showed a negative correlation with bone marrow involvement at the time of diagnosis (p = 0.028, ρ = −0.38)." (PMID 41373408, 2025).